PLIN4 (perilipin 4)
Description:
May play a role in triacylglycerol packaging into adipocytes. May function as a coat protein involved in the biogenesis of lipid droplets (By similarity).
Synonyms: KIAA1881; S3-12; MDRV; MRUPAV
Tractability: Antibody: its Gene Ontology location is reachable by antibodies, with high confidence; UniProt places it where antibodies can reach, with medium confidence; the Human Protein Atlas places it where antibodies can reach. PROTAC: its protein half-life has been measured.
Gene: Protein-coding gene on chromosome 19 (4,502,182 to 4,520,379, reverse strand). Ensembl gene ENSG00000167676.
Subcellular location: Cell membrane; Cytoplasm; Lipid droplet
Subcellular location (Human Protein Atlas): Cytosol; Plasma membrane; Lipid droplets
Pathways (Reactome):
Gene expression (Transcription): MLL4 and MLL3 complexes regulate expression of PPARG target genes in adipogenesis and hepatic steatosis
Gene Ontology:
Cellular component: cytosol; lipid droplet; plasma membrane; cytoplasm
Genetic constraint (gnomAD): Loss-of-function variants: 53 observed, 44.67 expected, observed/expected ratio (o/e) 1.19, 90% interval 0.95 to 1.49. The synonymous counts are far from expectation, so gnomAD's model fits this gene poorly and the ratio says little. Missense variants: 1,705 observed, 1,552.2 expected, observed/expected ratio (o/e) 1.1, 90% interval 1.05 to 1.14. Synonymous variants: 804 observed, 645.55 expected, observed/expected ratio (o/e) 1.25, 90% interval 1.17 to 1.32.
Homologues: Orthologues: chimpanzee PLIN4 (87% identical), macaque PLIN4 (76% identical), dog PLIN4 (67% identical), pig PLIN4 (66% identical), mouse Plin4 (59% identical), rat Plin4 (58% identical), zebrafish plin3 (8% identical), Drosophila melanogaster Lsd-2 (4% identical). Paralogues in human: PLIN3 (10% identical), PLIN2 (9% identical), PLIN5 (8% identical), PLIN1 (6% identical).
Diseases named in the same sentence as PLIN4 in open-access papers:
PLIN4 is named in the same sentence as 47 diseases in open-access papers, as found by Europe PMC text mining. Sharing a sentence is not in itself a finding about the gene and the disease. The quoted sentences say what the papers report.
Obesity (14 papers, 2011 to 2026). Accumulation of substantial excess body fat. "A SNP at PLIN4 locus was reported, and its variant alleles were associated with lower obesity risk in women." (PMID 38677512, 2024). "PLIN4 is located on chromosome 19 and is a member of the perilipin family that is implicated in adipocyte stability and obesity." (PMID 35384527, 2022). "Some patients were carriers of polymorphisms PLIN4 -11482G > A-, fat mass and obesity-associated (FTO) -rs9939609 A/T- and β-adrenergic receptor 3 (ADRB3) -Trp64Arg." (PMID 29361938, 2018). "Polymorphisms of the APOB, APOE, ADIPOQ, PLIN4, and HSD11β1 genes are important examples of genetic causes associated with dyslipidemias and obesity." (PMID 30507998, 2018). "PLIN4 was selected for further investigation because it is associated with obesity, insulin resistance and increased blood lipids." (PMID 25651499, 2015). "Plin4 is associated with insulin resistance and obesity risk." (PMID 31281445, 2019). "Administration of GC and GNN reduce weight and improve lipid and glucose blood profiles in people with overweight or obesity, although the presence of polymorphisms PLIN4, FTO and ADRB3 might hinder in some degree these effects." (PMID 29361938, 2018). "Associations between seven single nucleotide polymorphisms(SNPs) at human PLIN4 with obesity related phenotypes wereinvestigated using meta-analysis followed by a determination if these phenotypesare modulated by interactions between PLIN4 SNPs and dietaryPUFA." (PMID 21533135, 2011). "However, aswith the case of FTO and BMI, common variants modulatinganthropometric traits often explain only a small amount of the observed phenotypicvariation.It is likely that variation at PLIN4 is yet another contributor tothe complex nature of obesity and its associated comorbidities." (PMID 21533135, 2011). "Expression of PLIN4, which can prevent lysosomal degradation of cytosolic lipid droplets, was increased with age in WT mice and by both ethanol and obesity in 3xTg‐AD mice, whereas PLIN2 and PLIN3, which promote lysosomal degradation, were reduced." (PMID 40677154, 2025). "On the other hand, it has been reported that PLIN gene (located in chromosome 15) and with several described polymorphism such as PLIN1 6209 T → C, PLIN4 11482G → A and PLIN6 14995A → T have been associated with obesity development or protection." (PMID 29361938, 2018). "However, polymorphisms in perilipin 4 (PLIN4; −11482G > A), FM and obesity-associated (FTO; rs9939609 (A/T)), and β-adrenergic receptor 3 (ADRB3; Trp64Arg) attenuated its lipolysis effect." (PMID 37764380, 2023). "Weinvestigated how genetic drift in the PLIN4 3′UTR incombination with environmental exposures may act in concordance, predisposingindividuals to obesity." (PMID 21533135, 2011). "In our WD intervention in female mice, it is possible that redirection of lipids to WAT may have protected the livers of Plin4−/− mice at the earlier stages of the intervention and prevented the development of obesity-related metabolic complications in that organ." (PMID 41391763, 2025). "We can only speculate how lower expression of PLIN4 contributes to obesity-relatedphenotypes." (PMID 21533135, 2011). "In individuals with obesity, we found in the VAT an upregulation of PLIN1 and PLIN4, which belong to the class of perilipins, highly phosphorylated adipocyte proteins localized at the surface of lipid droplets." (PMID 41077621, 2026). "However, 4/11 have known or potential roles in obesity, MYO1C, PLIN4, PARD3 and PDE7B." (PMID 25651499, 2015).
Hepatic steatosis (7 papers, 2016 to 2024). Steatosis is a term used to denote lipid accumulation within hepatocytes. "There was a significant increase of genes associated with hepatic steatosis (Cidea, Cidec, and Plin4) and fibrosis (Col1a1) in Adn-Lpin1–/– livers on both diets compared with their diet-matched control mice." (PMID 39405118, 2024). "However, perilipin proteins are expressed in liver steatosis, and PLIN4 has been associated with increased PPARγ expression and hepatic lipid accumulation." (PMID 34835949, 2021). "From the current study, the focus is mainly on the role of PLIN2 in liver steatosis, whereas our results bring to light the potential of PLIN4." (PMID 34204055, 2021). "The role for Plin4 in hepatic steatosis is limited, but it may affect TAG accumulation during HFD feeding." (PMID 34128467, 2021). "Additionally, expression levels of Plin2, a marker for hepatic steatosis, as well as Plin3 and Plin4, genes thought to mediate formation of nascent droplets, were also significantly elevated, suggesting increased synthesis and packaging of triglycerides." (PMID 27097220, 2016).
breast carcinoma (5 papers, 2020 to 2025). "In addition, Perilipin 4 (PLIN4), a gene associated with lipid accumulation in other tissues and with breast cancer, was found in higher levels in low milk producers." (PMID 40929253, 2025). "In a novel departure from other studies, we found an up-regulation in the expressions of both canopy homolog 4 and perilipin (PLIN4) in stage 2 breast cancer tissues." (PMID 31945087, 2020). "Interestingly, LDs were found to co-localize with the mitochondria more frequently in chemo-resistant breast cancer cells, where the LD protein perilipin 4 (PLIN4) was increased." (PMID 35800362, 2022). "In breast cancer, the high expression of PLIN1 correlated with a good prognosis, but PLIN2 and PLIN4 expression correlated with a poor prognosis." (PMID 37998612, 2023). "And there was a co-expression relationship between AC108474.1 and 5 ferroptosis-related genes (TAZ, ISCU, CAV1, PLIN4, and HIC1), including 1 ferroptosis driver, 2 ferroptosis suppressor and 2 ferroptosis marker, and AC108474.1 was a protective factor for breast cancer patients too." (PMID 34164433, 2021). "PLIN4 assists in mobilizing lipids for oxidation from LDs, where silencing of PLIN4 decreased the growth of the chemotherapy-resistant, but not the parental, breast cancer cells, suggesting that lipid beta-oxidation is necessary for the sustained growth of chemotherapy-resistant cells." (PMID 35800362, 2022).
Insulin resistance (5 papers, 2015 to 2024). Increased resistance towards insulin, that is, diminished effectiveness of insulin in reducing blood glucose levels. "Fasting might also improve insulin resistance via upregulation of PLIN4 (Perilipin 4) expression, triggering similar effects as PPAR-γ (Peroxisome proliferator-activated receptor gamma) activators (e.g., pioglitazone)." (PMID 39545228, 2024). "The two perilipin genes PLIN4 and PLIN5 are known to be involved in lipid droplet coating and lipid metabolism, with PLIN5 playing a role in insulin resistance." (PMID 29409445, 2018).
metabolic syndrome (3 papers, 2018 to 2023). A cluster of metabolic risk factors for CARDIOVASCULAR DISEASES and TYPE 2 DIABETES MELLITUS. "Results were independent of sex, age or suffering from hypertension, diabetes mellitus type 2 or dyslipidemia and were attenuated in carriers of PLIN4, FTO, Trp64Arg polymorphisms." (PMID 29361938, 2018). "The upregulation of PKM M1/2 (pyruvate kinase M1/2, an enzyme involved in glycolysis) and PLIN4 (perilipin 4, a protein linked with cell lipid storage) expression indicates that IF may be highly effective in managing metabolic syndrome." (PMID 38068863, 2023).
pancreatic cancer (3 papers, 2015 to 2022). "It is likely that these myeloid cells and blood borne biomarkers of pancreatic cancer act in symphony to induce some of the observed local changes in the MBH, which is confirmed by the high level of co-regulation between a number of these transcripts (e.g. lrg1, Plin4, Lcn2 and Icam1)." (PMID 35031523, 2022).
Parkinson disease (3 papers, 2018 to 2025). A progressive degenerative disorder of the central nervous system characterized by loss of dopamine producing neurons in the substantia nigra and the presence of Lewy bodies in the substantia nigra and locus coeruleus. "Moreover, PLIN4 droplets have been observed in neurons and astrocytes in Parkinson’s disease moue model induced by MPP+57." (PMID 40216746, 2025). "Indeed, PLIN4 is upregulated in a mouse model of multiple sclerosis and Parkinson's disease where it appears to impact tyrosine-hydroxylase (TH)+ dopaminergic neuronal function." (PMID 35031523, 2022).
gastric cancer (2 papers, 2015 to 2024). A primary or metastatic malignant neoplasm involving the stomach. "Furthermore, PLIN4 mutations have been identified in gastric cancer and lung cancer and are associated with adverse prognosis." (PMID 38787520, 2024).
glioma (2 papers, 2023 to 2025). A benign or malignant brain and spinal cord tumor that arises from glial cells (astrocytes, oligodendrocytes, ependymal cells). "We also noticed that PLIN4 was also downregulated in glioma." (PMID 39870645, 2025).
liposarcoma (2 papers, 2020 to 2023). A usually painless malignant tumor that arises from adipose tissue. "In general, PLIN1 and PLIN4 might be of potential use as ancillary diagnostic indicators in liposarcoma." (PMID 32368290, 2020). "The expression rates of PLIN1 (P<0.001), PLIN2 (P=0.034), and PLIN4 (P<0.001) were significantly different in subtypes of liposarcoma, while the expression rates of PLIN3 (P=0.25) and PLIN5 (P=0.051) were not significantly different." (PMID 32368290, 2020). "It is worth noting that the expression of PLIN1 and PLIN4 in various subtypes of liposarcoma are still similar." (PMID 32368290, 2020). "PLIN4 expressed in some well-differentiated liposarcomas, including most WDLs (11/14), and a few MLs (10/38), but was absent in DLs (0/11) and PLs (0/3)." (PMID 32368290, 2020). "Both PLIN1 and PLIN4 also had a significant difference in liposarcoma subtypes (both P<0.001)." (PMID 32368290, 2020). "PLIN1 and PLIN4 expressions in liposarcoma were higher (both P<0.001) than those in non-lipomatous sarcoma." (PMID 32368290, 2020). "PLIN4 expression was shown in some liposarcomas (21/66) and was almost negative in non-lipomatous sarcomas (2/179)." (PMID 32368290, 2020). "It suggests that PLIN1 and PLIN4 were more important in identifying liposarcoma and non-lipomatous sarcoma that contained some specific overlapping diagnostic cells." (PMID 32368290, 2020). "The results showed that the expression levels of PLIN1 (P<0.001) and PLIN4 (P<0.001) in liposarcoma were significantly higher than those in non-lipomatous sarcoma." (PMID 32368290, 2020). "Interestingly, the expression levels of PLIN1 and PLIN4 in liposarcoma and non-lipomatous sarcoma had similar results which showed almost no expression in non-lipomatous sarcoma." (PMID 32368290, 2020).
myotilinopathies (2 papers, 2023 to 2025). "To date, aggrephagy has been investigated only in a limited number of diseases, reveling a pathological role in a case of FHL1-rigid spine syndrome and in a small case series of sIBM, PLIN4-related myopathy, myotilinopathies and desminopathies and oculopharyngeal muscular dystrophy." (PMID 37176163, 2023).
neuroblastoma (2 papers, 2023 to 2024). Neuroblastoma (NB) is the most common solid, extracranial childhood tumor. "In conclusion, our results demonstrate a novel regulatory mechanism(s) by which B. breve MCC1274 reduces PLIN4 expression and LD formation in neuroblastoma cells undergoing oxidative stress." (PMID 36985364, 2023). "A study on Parkinson’s disease (PD) showed that PLIN4 downregulation decreased LDs storage, thereby enhancing survival in the SH-SY5Y human neuroblastoma cells and indicating a dysfunctional PLIN4/mitophagy axis in PD’s pathogenesis." (PMID 39030618, 2024).
triple-negative breast carcinoma (2 papers, 2020 to 2024). An invasive breast carcinoma which is negative for expression of estrogen receptor (ER), progesterone receptor (PR), and human epidermal growth factor receptor 2 (HER2). "At the same time, another member of the same family, PLIN4, has also been identified as a therapeutic target for triple-negative breast cancer." (PMID 33029112, 2020). "Overexpression of PLIN4 has been shown to promote drug resistance of triple-negative breast cancer." (PMID 39297796, 2024).
Cachexia (1 paper, 2022). Severe weight loss, wasting of muscle, loss of appetite, and general debility related to a chronic disease. "First, we found that Lcn2 KO mice had more moderate cachexia and correspondingly decreased induction of a subset of the DE genes found in our scRNAseq model, such as Plin4, Tmem252, and Ly6a." (PMID 35031523, 2022).
chronic gastritis (1 paper, 2015). Inflammation of the stomach that is chronic in nature. "We noticed that 6 somatic variations (ATXN3, PLIN4, PDZD2, MUC4, DMBT1 and DAB1) were simultaneously observed in triple samples of chronic gastritis, primary cancer and PM cancer." (PMID 26330360, 2015).
depression (1 paper, 2019). "Furthermore, the expression levels of Plin4, Sgk1 and Klf2 increased in the striatum samples of rat models of depression following administration of ketamine, and the expression of Dcaf12l1 decreased compared with the control group." (PMID 31281445, 2019). "The FoxO and mTOR signaling pathways may be involved in the underlying mechanism of the antidepressant effects of ketamine, and Plin4, Sgk1, Klf2 and Dcaf12l1 may be potential biomarkers for depression in N-methyl-D-aspartic acid receptor antagonist treatment." (PMID 31281445, 2019). "The current study indicated that Plin4, Sgk1, Klf2 and Dcaf12l1 were differentially expressed in depression models treated with ketamine, phencyclidine and memantine, which suggested that these genes may be the targets of the NMDA receptor antagonist treatment." (PMID 31281445, 2019).
epithelioid sarcoma (1 paper, 2020). An aggressive malignant neoplasm of uncertain differentiation, characterized by the presence of epithelioid cells forming nodular patterns. "PLIN4 expression was negative in non-lipomatous sarcomas (0/171), except for epithelioid sarcomas (2/8)." (PMID 32368290, 2020).
hepatoma (1 paper, 2020). "Drug-induced accumulation of lipid droplets in human hepatoma cells was associated with upregulation of PLIN4." (PMID 32189058, 2020).
nonalcoholic steatohepatitis (1 paper, 2022). "Hence, Plin4, Lpl, and Acadm might produce beneficial effects on preventing the progression of NAFLD to nonalcoholic steatohepatitis." (PMID 36105184, 2022).
sarcopenia (1 paper, 2025). Progressive decline in muscle mass due to aging which results in decreased functional capacity of muscles. "For example, in primary sarcopenia, ST detects IGF1 downregulation in Type I fibers together with DST, GATM, and PLIN4 upregulation in Type II fibers, indicating parallel anabolic failure in slow fibers and stress-induced cytoskeletal and metabolic remodeling in fast fibers." (PMID 40718353, 2025).
tumor (17 papers, 2015 to 2025). "Key genes, including CD36, FABP4, PLIN1, PLIN4, SCD5, and ACSLs, were consistently downregulated in tumor tissues, with further reductions observed in KRAS-mutated samples." (PMID 40860798, 2025). "Our finding that NA production by B. breve MCC1274 directly impacts LD formation by reducing PLIN4 expression reduction is interesting given that LD accumulation is a common phenomenon in tumor cells." (PMID 36985364, 2023). "Studies have shown that PLIN4 upregulation can increase the viability and drug resistance of tumor cells, and this process is likely to be closely related to the inhibition of ferroptosis." (PMID 36414988, 2022). "Several of the most highly induced genes, CHI3L1, GPX1, PLIN1, PLIN4, and JAK3, have been linked to enhanced growth or cell survival in other tumor types." (PMID 35787784, 2022). "Compared with the corresponding normal tissues, the expression of PLIN4 in BLCA tumor tissues was downregulated, and higher expression of PLIN4 was associated with better prognosis." (PMID 34422642, 2021). "ALOXB15, TP63 and PLIN4 were obviously downregulated in tumor samples compared to normal ones." (PMID 34715817, 2021). "Specifically, we observed a significant down-regulation of some of the most relevant genes in the PPAR pathway (CD36, FABP4, PLIN1, PLIN4, SCD5 and ACSL4) in tumor tissue samples." (PMID 40860798, 2025). "We determined mRNA expression profiles of PLIN1, PLIN2, PLIN3, PLIN4, and PLIN5 in a panel of OC cell lines and tumor tissue, using RT‐PCR." (PMID 41041279, 2025). "Results showed that some of the most relevant pathway’s regulators and effectors (CD36, FABP4, PLIN1, PLIN4, SCD5 and ACSL6) showed significantly lower expression in tumor tissue samples (p.adjusted < 0.01, data not shown)." (PMID 40860798, 2025). "The results demonstrated that the mRNA levels of PLIN1/PLIN4/PLIN5 were not correlated with tumor recurrence status, while PLIN2 and PLIN3 were correlated with tumor recurrence status." (PMID 37189627, 2023).